C5AR1 (complement C5a receptor 1)
Diseases named in the same sentence as C5AR1 in open-access papers (continued):
Sharing a sentence is not in itself a finding about the gene and the disease.
breast cancer (32 papers, 2018 to 2025). A primary or metastatic malignant neoplasm involving the breast. "It has been discovered that C5ar1‐positive neutrophils, a group of neutrophils linked to the growth of breast cancer, increase BC cell glycolysis via upregulating ENO1 expression." (PMID 40919129, 2025). "High C5aR1 levels in human breast cancers are associated with poor responses to immune checkpoint blockade." (PMID 38802355, 2024). "Xi Li provided evidence that C5aR1 inhibition reprograms tumor-associated macrophages in two murine breast cancer models: one intrinsically sensitive to PARP inhibitors (T22) and the other resistant (T127)." (PMID 39483473, 2024). "Several studies have demonstrated the existence of an association between high C5aR1 expression and poor outcomes in head and neck squamous cell carcinoma, gastric cancer, breast cancer, and glioblastoma." (PMID 37760630, 2023). "For example, activation of the complement components C5 and C5a in cancer tissues and expression of C5aR1 in breast cancer cells is linked to a poor prognosis." (PMID 36508191, 2023). "Consistently with TAM_C3, C5ar1_hi_C3 was dominantly associated with a worse outcome in TCGA basal breast cancer and when assessing contributions of cluster top DEG to outcomes in TCGA basal breast cancer by multivariate analysis, C5AR1 was associated with poor outcomes independently." (PMID 38802355, 2024). "C5aR1+ neutrophil overexpression in breast cancer is associated with poor survival." (PMID 36139062, 2022). "Moreover, C5a-C5aR1 signaling has been associated with cancer progression and poor prognosis in breast cancer patients." (PMID 33430104, 2021). "WTAP silencing reverses the influence that C5ar1‐positive neutrophils have on breast cancer development in vivo." (PMID 40919129, 2025). "The possibility of using C5AR1‐positive neutrophils as therapeutic targets for breast cancer is supported by this study." (PMID 40919129, 2025). "Maciej M. Markiewski demonstrated that ribosomal protein S19 interacts with C5aR1 and promotes breast cancer growth by facilitating the recruitment of MDSCs to tumors." (PMID 39483473, 2024). "Recent studies had found that C5aR1 was up-regulated in breast cancer, colon cancer, hepatocellular carcinoma, lung cancer, gastric cancer, kidney cancer, cervical cancer." (PMID 36192575, 2023). "In a syngeneic model of breast cancer for example, C5aR knockout mice or pharmacologic inhibition of C5aR1 reduced lung and liver metastatic burden, while CD8 T cells and inhibiting regulatory T cells were increased." (PMID 36003145, 2022). "C5aR1-positive neutrophils were found to promote breast cancer glycolysis, resulting in tumor progression and poor survival." (PMID 36497433, 2022). "RPS19, one of the DEGs in metastatic breast cancer cells, is an immunosuppressive molecule expressed by metastatic breast cancer cells, and its interaction with C5AR1 of macrophages was also identified in the metastases of five lymph nodes." (PMID 36148946, 2022). "Using two murine BC models (EMT6 and 4T1), treatment with a dual C3aR/C5aR1 agonist significantly slowed mammary tumor development and progression, suggesting that complement activation peptides can influence the anti-tumor response in different ways." (PMID 36294305, 2022). "In breast cancer, researchers found that C5aR1-positive neutrophils secrete IL-1-β and TNF-α and they cooperatively activate ERK1/2 signal and phosphorylate WTAP at serine 341 to stabilize WTAP protein." (PMID 35251177, 2022). "Collectively, our study reveals a novel subset of C5aR1-positive neutrophils that induces breast cancer glycolysis via increasing ERK1/2-WTAP-dependent m6A methylation of ENO1." (PMID 34312368, 2021). "Having established that C3a/C5aR1 agonism is effective in inhibiting mammary tumor growth in mice, we next explored possible mechanisms responsible for the anti-tumor effects." (PMID 33430104, 2021).
breast cancer (continued). "Syngeneic mouse models (cervical cancer, lung cancer, or breast cancer) revealed that C5a and its receptor C5aR1 are involved in the recruitment of MDSC." (PMID 33113844, 2020). "Utilizing a syngeneic mouse model of metastatic breast cancer, it has been demonstrated that C5aR1 knockout or wild-type mice administrated with a specific C5aR1 inhibitor (PMX-53) had decreased lung and liver metastatic burden compared to control mice." (PMID 30061895, 2018). "Moreover, Baochi Ou showed that C5aR1+ neutrophils enhance the glycolytic capacity of breast cancer cells through the ERK1/2-WTAP-ENO1 signaling pathway." (PMID 39483473, 2024). "In breast cancer, C5aR1 positive neutrophils can enhance the glycolysis of breast cancer cells." (PMID 37582735, 2023). "Moreover, various studies have shown that inhibition of the C5a/C5aR1 pathway can help in the management of breast cancer." (PMID 36508191, 2023). "C5AR1 was also shown to induce breast cancer glycolysis by regulating m6A methylation." (PMID 36230961, 2022). "The current study used two murine breast cancer models (EMT6 and 4T1) to investigate whether pharmacological targeting of receptors for complement proteins C3a (C3aR) and C5a (C5aR1) is protective in murine breast cancer models." (PMID 33430104, 2021). "C5a and C5aR1 are also highly expressed in a variety of tumors, such as cervical cancer, lymphoma, lung cancer, melanoma, breast cancer, ovarian cancer, cholangiocarcinoma, gastric cancer, renal cancer, lymphoma, liver cancer, colon cancer, pancreatic cancer, and glioma." (PMID 33869223, 2021). "However, treatment of mice with a dual C3aR/C5aR1 agonist (YSFKPMPLaR) significantly slowed mammary tumor development and progression." (PMID 33430104, 2021). "Importantly, C5aR1-positive neutrophils also promote breast cancer growth in vivo, and this effect is abolished by WTAP silencing." (PMID 34312368, 2021). "The present study demonstrated a protective role for C3aR/C5aR1 agonism in murine models of mammary carcinoma and suggests that this may be due to an enhanced T cell response." (PMID 33430104, 2021). "Examination of receptor expression by quantitative polymerase chain reaction (qPCR) analysis showed very low levels of mRNA expression for either C3aR or C5aR1 by EMT6 or 4T1 mammary carcinoma cell lines compared with the J774 macrophage line or bone marrow-derived macrophages." (PMID 33430104, 2021). "In these models, Rps19/C5aR1 signaling is selectively elevated in TAM_C3, which predominantly expresses genes associated with an anti-inflammatory/protumor state.However, whether C5a/C5aR pathway are involved in ferroptosis during breast cancer carcinogenesis remains unclear." (PMID 39483473, 2024). "The anti-tumoral effects of the agonist are regulated by the modulation of immune cell functions, as evidenced by the low mRNA expression of C3aR and C5aR1 detected in EMT6 and 4T1 mammary carcinoma cell lines by qPCR analysis." (PMID 41300283, 2025). "Other studies have shown that C5AR1‐positive neutrophils can also release inflammatory factors such as IL1 β, TNF α and ENO1, which are known to promote tumour progression in breast cancer." (PMID 39580709, 2024). "Recently, it has been shown that C3aR and C5aR1 signaling have an important impact on the IL-10-mediated cytotoxic properties of CD8+ T cells infiltrating tumors in models of melanoma and breast cancer (E0771)." (PMID 30061895, 2018). "Mechanically, IL1β and TNFα secreted by C5aR1 positive neutrophils can act on the downstream ERK1/2-WTAP-ENO1 signal axis, increase the m6A modification level of ENO1 mRNA, and promote ENO1 expression and glycolysis in breast cancer cells." (PMID 37582735, 2023). "However, treatment with a dual C3aR/C5aR1 agonist (EP54) inhibited development and growth of both EMT6 and 4T1 mammary tumors." (PMID 33430104, 2021).
breast cancer (continued). "To determine whether C5aR1 expression on macrophages has the potential to alter response to ICB, we assessed correlations between C5aR1 expression in a breast cancer scRNA-seq dataset of patients receiving anti-PD-1 where treatment response was estimated by T cell expansion." (PMID 38802355, 2024).
lung carcinoma (30 papers, 2016 to 2025). "Similar findings have been observed in lung cancer, and meta-analyses have shown a higher level of C5aR1 associated with the occurrence of lymph node metastases." (PMID 40056975, 2025). "In 2012, using a lung cancer model, we first demonstrated an association between the inhibition of C5a receptor 1 (C5aR1) and the expression of PD-L1 within the tumor microenvironment." (PMID 31031765, 2019). "The C5AR1 gene, coding for the G protein-coupled receptor for complement component 5a, plays an important role in the innate immunity regulation and tolerance and may be linked to immune checkpoints, as they relate to lung cancers." (PMID 33059718, 2020). "C5aR1 is expressed across a spectrum of immune and neoplastic cell lineages, including lung carcinoma cells." (PMID 39512767, 2024). "In animal models of lung cancer, gastric cancer and ovarian cancer, downregulation, silencing or inhibition of C5aR1 can reduce tumor proliferation, angiogenesis, tumor growth and metastasis." (PMID 36192575, 2023). "In previous studies, when C5aR1 was silenced, the skeletal metastatic burden and osteolysis increased in lung cancer, indicating that C5aR1 had metalloproteolytic, migratory and invasive abilities in tumor cells." (PMID 36213507, 2022). "As described, the C5a/C5aR1 axis is widely expressed in tumors, such as cervical cancer, lymphoma, lung cancer, and glioma, and participates in disease occurrence and development." (PMID 33869223, 2021). "CXCL16 expression also depends on receptors, e.g., complement C5a receptor 1 (C5aR1) in lung cancer cells." (PMID 33800554, 2021). "CXCL16 has been described this year to play an important role in C5aR1 signaling related osteoclastogenic activity in lung cancer cells, impairing osseous colonization." (PMID 31897234, 2020). "It is interesting to note that genes such as C5AR1, CHRNA4 and HTR1A from the neuroactive ligand receptor pathway have been reported in association with PAH, lung cancer, COPD and idiopathic pulmonary fibrosis." (PMID 31324852, 2019). "Accordingly, pharmacological blockade of C5aR1 in a syngeneic model of lung cancer impaired tumor growth, decreased the percentage of splenic MDSCs, and downregulated immunosuppression-related genes including ARG1, IL6, IL10, CTLA4, LAG3, and PDL1 within the tumor milieu." (PMID 31001273, 2019). "Furthermore, C5aR1 inhibition hampers lung cancer cell migration, and up-regulates the expression of E-cadherin, suppressing EMT and invasiveness." (PMID 31001273, 2019). "Moreover, C5aR1 also promotes bone metastasis of lung cancer by CXCL16-mediated effects." (PMID 30686982, 2018). "Furthermore, other research showed that the blockade of C5aR1 in combination with the blockade of PD-1 could restore antitumor immune responses, inhibit tumor cell growth, and improve the outcomes of patients with lung cancer." (PMID 36213507, 2022). "Joint blockade of complement C5a receptor 1 (C5AR1) and PD-1 prevented lung cancer metastasis and improved the prognosis of patients." (PMID 34266411, 2021).
Alzheimer disease (26 papers, 2009 to 2025). A progressive, neurodegenerative disease characterized by loss of function and death of nerve cells in several areas of the brain leading to loss of cognitive function such as memory and language. "Through GO and KEGG analyses, we further identified that C5aR1 was associated with Alzheimer’s disease-related pathways and tumor development-related pathways, e.g., the MAPK signaling cascade." (PMID 37760630, 2023). "As such, the C5a-C5aR1 axis has been implicated in proinflammatory signaling in several neuroinflammatory conditions, including ischemic stroke, spinal cord injury and Alzheimer’s disease." (PMID 37308987, 2023). "C5a and C5AR1 have also been associated with disease processes such as ischemia-reperfusion injury, rheumatoid arthritis, asthma, immune complex diseases, neurodegeneration and Alzheimer's disease." (PMID 32471891, 2020). "Among the top targets identified from druggability analysis, four of them (i.e., DRD2, C4B, GABA-A-R, C5AR1) were shown in the single-nuclei sequencing data because of their clinical relevance to inflammation involved in Alzheimer’s disease." (PMID 39897171, 2024). "C5AR1 has been proven to play a crucial role in regulating inflammatory and neurocognitive functions in IS, Alzheimer’s disease, malaria, and neuropathic pain." (PMID 38650649, 2024). "While the specific role of C5aR1 in synaptic pruning during Alzheimer's disease (AD) pathogenesis is still not fully understood, there have been several recent publications demonstrating key roles of the complement system in both synaptic pruning and AD." (PMID 38278523, 2024). "Genetic ablation of C5aR1 delayed/decreased microglial population in an experimental model of Alzheimer’s disease." (PMID 37443787, 2023). "Previously, genetic ablation of C5aR1 in a mouse model of Alzheimer’s disease exerted a protective effect by preventing cognitive deficits." (PMID 35978440, 2022). "In summary, here, we provide evidence of a neuroprotective effect of the pharmacological inhibition of C5a-C5aR1 signaling in the pathology progression in the Tg2576 mouse model of Alzheimer’s disease." (PMID 35978440, 2022). "C5aR1 ablation in the Arctic (Arc) model of Alzheimer’s disease protects against cognitive decline and neuronal injury without altering amyloid plaque accumulation." (PMID 35820938, 2022). "Together, our results demonstrated a neuroprotective and beneficial effect of blocking C5a-C5aR1 signaling in the Tg2576 mouse model of Alzheimer’s disease." (PMID 35978440, 2022). "Our data further supports the use of C5aR1 antagonists as potential therapeutic targets to treat or slow the progression of Alzheimer’s disease." (PMID 35978440, 2022). "We and others have previously reported several beneficial effects of this C5aR1 antagonist, not only in Alzheimer’s disease but also in amyotrophic lateral sclerosis and spinal cord injury and other CNS disorders." (PMID 35978440, 2022). "In an Alzheimer’s disease mouse model, knock out of C5aR1 prevented spatial memory cognitive deficits at 10 months of age, likely through reduction of inflammatory responses." (PMID 30987383, 2019). "Pharmacologic inhibition of C5aR1, a receptor for the complement activation proinflammatory fragment, C5a, suppressed pathology and cognitive deficits in Alzheimer's disease (AD) mouse models." (PMID 28923083, 2017). "The data supports further investigation of the use of antagonists for C5aR1 as part of a novel therapeutic strategy to slow the progression of Alzheimer’s disease cognitive decline." (PMID 28923083, 2017). "The upregulation of C5aR1 is proved to be detrimental in many neurodegenerative diseases, for example, Alzheimer's disease (AD), amyotrophic lateral sclerosis (ALS), and Huntington's disease (HD)." (PMID 28706957, 2017). "Additionally, while not entirely unstudied, not much research has been conducted evaluating antagonists that target C5AR1 while considering Alzheimer’s disease." (PMID 38276010, 2024).
Alzheimer disease (continued). "Furthermore, knockout of C5AR1 in a mouse-based Alzheimer’s disease model also exhibited less inflammation and inhibited memory deficit in the hippocampal area." (PMID 35387346, 2022). "Furthermore, the gene profile of microglia showed less inflammation and a higher induction of clearance pathways after the genetic ablation of C5aR1 in an Alzheimer’s disease mouse model." (PMID 32676862, 2020). "The data support further exploration of C5aR1 antagonists as therapy in Alzheimer's disease." (PMID 28078911, 2017). "Genetic deletion of C5aR1 in the Arctic Alzheimer’s disease mouse model resulted in protection from loss of neuronal complexity in CA1 neurons and prevented deficits in a hippocampal dependent spatial memory task relative to the C5aR1 sufficient Arctic animals." (PMID 28923083, 2017). "Research has proved that C5AR1 (also named CD88) played an important role in the regulation of inflammation and neurocognitive functions in ischemic stroke, Alzheimer’s disease, malaria, and neuropathic pain." (PMID 35387346, 2022). "Here, we used the Tg2576 mouse model of Alzheimer’s disease and treated them with PMX205 at the onset of the amyloid pathology to further determine the effects of this C5aR1 antagonist on microglial cells." (PMID 35978440, 2022). "Previous work demonstrated that the C5aR1 antagonist, PMX205, decreased amyloid pathology and suppressed cognitive deficits in two Alzheimer's Disease (AD) mouse models." (PMID 28078911, 2017).
rheumatoid arthritis (25 papers, 2008 to 2025). A chronic, systemic autoimmune disorder characterized by inflammation in the synovial membranes and articular surfaces. "Avdoralimab, a specific anti-C5aR1 monoclonal antibody, has already shown a good safety profile in the treatment of solid tumors and rheumatoid arthritis." (PMID 36359364, 2022). "Additionally, Phase I clinical trials have demonstrated that PMX53, a cyclic peptide acting as a C5aR1 antagonist, is safe for oral administration in the treatment of rheumatoid arthritis." (PMID 39850877, 2024). "In hard to treat rheumatoid arthritis (RA) patients, conjugation of siRNA against C5 complement’s component with C5a receptor 1 (C5aR1)-specific Ab showed 83% reduction in RA-related symptoms compared to only 19% when siRNA and Ab were delivered unconjugated." (PMID 36411594, 2022). "In this review, we will analyze the role of C5a-C5aR1 axis in bone physiology and pathophysiology, describing its involvement in the pathogenesis of some of the most frequent inflammatory bone diseases such as rheumatoid arthritis, and also in osteoporosis and bone cancer and metastasis." (PMID 36003145, 2022). "In this mini-review, we will discuss the role of the C5a-C5aR1 axis in bone physiology and pathology, focusing on its involvement in the pathogenesis of inflammatory disorders of the skeletal system, as in particular rheumatoid arthritis, and also osteoporosis and cancer metastasis to the bones." (PMID 36003145, 2022).
ANCA-associated vasculitis (20 papers, 2018 to 2025). "CCX168, a selective C5aR1 inhibitor for ANCA-associated vasculitis, has demonstrated clinical efficacy, although its potential antitumour effects in oncology are yet to be explored." (PMID 41044172, 2025). "Blockade of C5aR1 prevented disease expression, and C5aR2 deficiency aggravated the disease condition; antagonism is being tested as a therapy for patients with ANCA-associated vasculitis." (PMID 32228220, 2020). "The C5 blocking monoclonal antibody (mAb) eculizumab has been successfully used for PNH for >10 years and a specific C5aR1 antagonist (avacopan) has been filed for Food and Drug Administration approval for the treatment of antineutrophil cytoplasmic antibody-associated vasculitis." (PMID 34099640, 2021). "A clinical trial in patients with ANCA-associated vasculitis has shown that a C5aR1 antagonist is beneficial and may reduce the need for corticosteroids in this disease." (PMID 31636644, 2019). "For example, the C5aR1 antagonist avacopan (AVA, ChemoCentryx, Mountain View, CA) has shown therapeutic efficacy in ANCA-associated vasculitis in a phase III clinical study, supporting the utility of C5aR1 antagonists in human disease." (PMID 34899737, 2021).